SCARNA11 (small Cajal body-specific RNA 11)
Synonyms: ACA57
Gene: Small Cajal body-specific RNA gene on chromosome 12 (6,581,474 to 6,581,609, reverse strand). Ensembl gene ENSG00000251898.
Gene Ontology:
Biological process: RNA processing
Cellular component: Cajal body; nucleolus
Homologues: Orthologues: chimpanzee SCARNA11 (100% identical), guinea pig SCARNA11 (93% identical), rabbit SCARNA11 (86% identical).